BRCA1 (BRCA1 DNA repair associated)
Diseases named in the same sentence as BRCA1 in open-access papers (continued):
Sharing a sentence is not in itself a finding about the gene and the disease.
ovarian carcinoma (continued). "For breast and ovarian cancer risk assessment in the isolated populations of the Northern Isles of Orkney and Shetland (in Scotland, UK) and their diasporas, quantifying genetically drifted BRCA1 and BRCA2 pathogenic variants is important." (PMID 39438716, 2024). "Mutations in ARID1A have been reported in BRCA1 mutated ovarian cancer." (PMID 38940864, 2024). "An estimated 1 in 350 women carry germline BRCA1/2 mutations, which confer an increased risk of developing breast and ovarian cancer, and may also contribute to subfertility." (PMID 39084071, 2024). "Reasons for exclusions were single arm studies, drug taken off the market due to lack of efficacy in a post-marketing trial (olaratumab for soft-tissue sarcoma), and data unavailable despite contact with study authors (olaparib maintenance in relapsed BRCA1/2-mutated ovarian cancer)." (PMID 38172190, 2024). "Mutations in the BRCA1/2 genes significantly increase the risks for breast and ovarian cancer." (PMID 38192174, 2024). "After analyzing the database with pathogenic mutations most frequently identified in BRCA genes and excluding studies with overlapping samples, we can verify that the c.5266dupC mutation in BRCA1 is the most commonly found in Brazil in patients with breast and/or ovarian cancer." (PMID 38504328, 2024). "The latest follow-up studies in the SOLO1 ovarian cancer maintenance trial showed that olaparib significantly improved the overall survival (OS) of advanced ovarian cancer patients carrying BRCA1/2 mutations after seven years, marking it the first PARPi shown to provide an OS benefit." (PMID 39007266, 2024). "In a clinical cohort of ovarian cancer, epigenetic inactivation of BRCA1 was linked to a better response to cisplatin treatment and increased overall survival, suggesting that BRCA1 methylation affects the efficacy of cisplatin therapy and hence, the clinical outcome in this type of tumor." (PMID 38256203, 2024). "Since the discovery of a BRCA1 mutation nearly 30 years ago, definitive methods for ovarian cancer-risk reduction has remained unchanged, requiring carriers of a pathogenic mutation to consider undergoing surgical removal of both fallopian tubes and ovaries from the ages of 35 to 40 years." (PMID 38539519, 2024). "Interestingly, three out of four patients with platinum-resistant ovarian cancer treated by paclitaxel have a decrease of BRCA1/2 reversion mutation, as suggested by the analysis of pre- and posttreatment samples." (PMID 38544832, 2024). "The UWB1.289 ovarian cancer cell is HR deficient, harboring a BRCA1 mutation." (PMID 37861290, 2023). "Ovarian cancer patients with BRCA1/2 mutations were inherently more sensitive to platinum-based chemotherapy than patients with wild-type ovarian cancer, and the benefits of using PARPi inhibitors versus platinum-based chemotherapy at the same relapse stage were still uncertain." (PMID 37891662, 2023). "PARPi were successfully used in breast and ovarian cancers with the BRCA1/2 deficiency." (PMID 37169803, 2023). "We demonstrated that PSPC1 inhibition enhanced olaparib efficacy in a preclinical model of breast or ovarian cancer with BRCA1/2 mutations compared to olaparib alone, suggesting a promising therapeutic alternative to enhancing PARP inhibitor sensitivity in non-resistance settings." (PMID 38069409, 2023). "BRCA1/2 germline mutations are the strongest known genetic risk factors for epithelial ovarian cancer and are found in 6–16% of patients, and treatment with poly (ADP-ribose) polymerase inhibitors (PARPi) has a significant response based on “synergistic lethal effects”." (PMID 37891662, 2023).
ovarian carcinoma (continued). "Furthermore, early studies of PARPis showed promising results in BRCA1/2-deficient cells, which built the foundation for clinical trials investigating PARPi response in ovarian cancer." (PMID 38067337, 2023). "When a BRCA1/2 reversion mutation was identified in pretreatment samples from patients with ovarian cancer receiving rucaparib, the median progression-free survival (PFS) was noted to be shorter compared with those without reversion mutations (1.8 months versus 9 months)." (PMID 37430137, 2023). "Of the predicted pathogenic (i.e., loss-of-function) BRCA1/2 variants in ovarian cancer that had been discarded (n = 2), one variant is characterized as ‘Pathogenic’ by a single submitter (BRCA1 S324fs*17; ClinVar Variation ID: 946287), while the other is absent from the database (BRCA2 I979fs*12)." (PMID 37568048, 2023). "Consequently, olaparib is mainly investigated in the context of BRCA-deficient cancer types and has already been approved by the European Medicines Agency (EMA) and US FDA for the treatment of recurrent ovarian cancer in BRCA1/2-mutated women." (PMID 36978917, 2023). "Individuals with a germline BRCA1 mutation carry a 39–46% risk of developing ovarian cancer." (PMID 37108451, 2023). "Studies in prostate and ovarian cancer have suggested that some patients with somatic BRCA1/2 (sBRCA1/2) mutation or mutations in HR-related genes other than BRCA1/2 may benefit from PARP inhibitors." (PMID 38098088, 2023). "Some studies suggest that a higher intake of supplemental selenium may be inversely related to ovarian cancer risk, especially in women with BRCA1 mutations." (PMID 37446063, 2023). "Moreover, detectable in blood methylation of BRCA1 gene has been proposed as biomarker of predisposition to breast and ovarian cancers." (PMID 37434214, 2023). "However, patients with BRCA1 mutations tend to have a higher risk of developing ovarian cancer by the age of 80; 44% (95% C.I, 36%-53%) for BRCA1 and 17% (95% C.I, 11%-25%) for BRCA2." (PMID 38017453, 2023). "Of the 30 ovarian carcinomas from the test cohort, 6 showed a mutation in BRCA1 and 5 in BRCA2." (PMID 38139296, 2023). "About 15% of ovarian cancer patients have a germline mutation in the BRCA1 or BRCA2 genes, and in these cases, chemotherapy can be supplemented with the administration of PARP inhibitors, which limit the regeneration of the cells as well as the further growth and proliferation of the tumor cells." (PMID 36856946, 2023). "In December of 2014, the Food and Drug Administration (FDA) approved olaparib (LYNPARZA, KuDOS/AstraZeneca), a first-in-class PARP inhibitor (PARPi), to treat patients with advanced ovarian cancers and also with BRCA1/2 mutations who have previously been treated with multiple rounds of chemotherapy." (PMID 37035242, 2023). "BRCA1/2 mutations account for 5 to 10% of breast and 15% of ovarian cancers." (PMID 37723374, 2023). "This knowledge could be instrumental in developing innovative therapies tailored to the specific molecular characteristics of breast and ovarian cancers associated with BRCA1 dysfunction." (PMID 37762577, 2023). "Germline BRCA1/2 pathogenic variants are predictive and prognostic biomarkers in ovarian cancer." (PMID 36765687, 2023). "In December 2014, the FDA approved the first PARP inhibitor, olaparib, as a monotherapy for patients with advanced BRCA1/2-mutated ovarian cancer who were treated with three or more prior lines of chemotherapy based on the promising results from a Phase II clinical trial (NCT0107662)." (PMID 37035242, 2023). "Mutations in BRCA1/2 increase the lifetime risk of ovarian cancer development by 40%." (PMID 36900195, 2023).
ovarian carcinoma (continued). "A report was published of a severe phenotype patient with ovarian cancer at age 28, short stature, microcephaly and significant toxicity from chemotherapy, with compound heterozygous BRCA1 variants, c.2457delC, and c.5207T > C; as well as loss of heterozygosity in associated tumours." (PMID 36927983, 2023). "BRCA1/2 mutations are the generally observed major mutations in ovarian cancer." (PMID 37110218, 2023). "BRCA1 mutations are frequently found in hereditary ovarian cancers." (PMID 37110218, 2023). "Patients with BRCA1/2-mutated recurrent ovarian cancer may respond to platinum-based and other chemotherapy agents that induce direct DNA damage." (PMID 37916177, 2023). "Since the study period, recommendations for genetic testing have evolved to include most women with ovarian cancer, mainstreaming of genetic testing, and inclusion of a test to detect germline pathogenic BRCA1 or BRCA2 genetic variants in the MBS from 2017, at a cost of ~$1,000 per eligible person." (PMID 37071628, 2023). "The SOLO2 clinical trial was a Phase III, double-blinded, randomized, placebo-controlled study that evaluated the use of olaparib as maintenance therapy in platinum-sensitive, relapsed ovarian cancer patients with a BRCA1/2 mutation who had received at least two lines of previous chemotherapy." (PMID 37035242, 2023). "This unexpectedly low prevalence of BRCA1 Exon 13 duplication contradicts previous prevalence data from North American/European cohorts of patients at risk of hereditary breast and/or ovarian cancer, where this large rearrangement was the fourth most common germline BRCA1 pathogenic variant." (PMID 38201604, 2023). "Women diagnosed with breast and/or ovarian cancer or with a family history of these types of cancers can undergo genetic counseling to investigate whether they carry the BRCA1/2 genetic mutation." (PMID 37706348, 2023). "Our findings could potentially be used as an orientation for clinical experts and decision makers in Germany to guide further improvements in the management strategies for BRCA-1/2 mutation carriers and breast and/or ovarian cancer prevention." (PMID 37365514, 2023). "The median GIS was 62 in BRCA1/2-deficient ovarian cancer tumors and 31 in BRCA-intact tumors." (PMID 37589839, 2023). "Therefore, the objective of the present study was to create two isogenic in vitro models of PARPi-resistant ovarian cancer derived from a BRCA1-wildtype (HR-proficient) vs. BRCA1-mutated (HR-deficient) genetic background." (PMID 37568590, 2023). "More than 40% of BRCA1/2-mutated ovarian cancers treated in the clinic fail to respond to PARPi." (PMID 37609662, 2023). "BRCA1/2 mutations are known to increase risk of breast and ovarian cancer but carrier status in healthy individuals is unknown without genetic testing." (PMID 37291133, 2023). "In the US, only about 5–10% of breast and ovarian cancers are associated with mutations in BRCA1/2." (PMID 36981032, 2023). "The high success rate of PARPi in breast and ovarian cancers might be attributed to a subset of these cases enriched with BRCA1/2 pathogenic variants and a sensitive threshold to distinguish HR deficient and HR proficient tumors." (PMID 37761823, 2023). "The aim of this study was to report the concordance of BRCA1/2 pathogenic/likely pathogenic variants detected in germline and tumour DNA in a large, real-world cohort of patients treated for epithelial ovarian cancer at our specialist oncological referral centre." (PMID 38201604, 2023).
ovarian carcinoma (continued). "We investigated whether this BRCA1 variant was also present in a Dutch cohort of breast and ovarian cancer patients with tumor BRCA1 promoter hypermethylation." (PMID 36112334, 2023). "The GIS distribution of BRCA1/2-deficient tumors for ER + BC was significantly different from the distribution for ovarian cancer, indicating that the GIS threshold used for ovarian cancer may not be appropriate for ER + BC." (PMID 37589839, 2023). "The aim of this study was to assess the power of the polygenic risk score (PRS) in estimating the overall genetic risk of women carrying germline BRCA1 pathogenic variants (PVs) c.4035del or c.5266dup to develop breast (BC) or ovarian cancer (OC) due to additional genetic variations." (PMID 37296919, 2023). "Knowledge of a BRCA1/2 mutation in healthy patients may allow prophylactic measures to be taken that can reduce the incidence of breast and ovarian cancer and reduce mortality in this population." (PMID 37723374, 2023). "This study has identified BRCA1 as the main contributor to the familial ovarian cancer risk in this country and has uncovered novel variants in additional genes that will deserve consideration in further studies of hereditary ovarian cancer." (PMID 37013556, 2023). "Moreover, it has been demonstrated that GTFII-I interacts with BRCA1, a tumor suppressor gene product mutated in breast and ovarian cancers." (PMID 37021113, 2023). "HRD has been observed not only in ovarian cancer patients with germline or somatic BRCA1 or BRCA2 mutations but also in those with epigenetic silencing of BRCA1 or loss of function of other genes, such as ATM, ATR, BARD, BRIP, EMSY, PALB2, RAD51, and Fanconi Anemia Complementation Group genes." (PMID 36836518, 2023). "Reversion mutations have been reported in circulating tumour DNA of up to 39% of patients with BRCA1/2-mutated prostate cancer after progression on rucaparib, and approximately 24% of patients with ovarian cancer after treatment with platinum chemotherapy and PARPi." (PMID 37430137, 2023). "This resistance may be tied to STAT3 activation in tumor cells in the case of PARPi-resistant BRCA1-deficient murine ovarian cancer." (PMID 38139802, 2023). "However, BRCA1/2 carriers predominantly develop ovarian cancer, while NCBP1 carriers are more predisposed to cervical cancer." (PMID 38136334, 2023). "The BRCA1/2 genetic tests are used to predict women at a high risk of breast and ovarian cancers." (PMID 36981032, 2023). "The importance of BRCA1 is particularly evident in studies on BRCA1-mutant cells; a loss-of-function mutation increases the likelihood of tumor formation, particularly breast and ovarian cancer." (PMID 37762697, 2023). "PARPi monotherapy was similar to platinum-based chemotherapy for BRCA1/2-mutated ovarian cancer patients with secondary platinum-sensitive recurrence, and could improve prognosis." (PMID 37891662, 2023). "The presence of a BRCA1 mutation was detected in 6 cases (24% of all groups with ovarian cancer)." (PMID 37373969, 2023). "On the other hand, skewed XCI has been described at an increased frequency in BRCA1 mutation carriers compared with controls, and is associated with a statistically significant increase in age at diagnosis of breast and ovarian cancer in BRCA1/BRCA2 GPV carriers." (PMID 38069345, 2023). "However, more than 40% of BRCA1/2-mutated ovarian cancer lack the initial response to PARPi treatment, and the majority of those that initially respond eventually develop resistance." (PMID 37429899, 2023). "In Japan, though comprehensive genomic profiling can be conducted to test for somatic BRCA1/2 mutations, its wide application in clinical practice is hampered by its high cost and the reservation of testing in patients with primary ovarian cancer who cannot be treated with standard therapy." (PMID 37488223, 2023).
ovarian carcinoma (continued). "One study of 235 ovarian cancers found that 19% harboured either germline or somatic BRCA1/2 mutations and may, therefore, be amenable to PARPi treatment." (PMID 37108451, 2023). "Besides, a study demonstrated that BRCA1 was a tumor suppressor gene with the mutated phenotype predisposed to breast and ovarian cancer." (PMID 36726489, 2023). "For instance, siRNAs targeting the DNA repair machinery have been used to mimic the activity of PARP inhibitors and the administration of a lipidoid-siPARP1 nanoparticle in a BRCA1-deficient ovarian cancer mouse model successfully reduced tumor growth by causing the activation of apoptosis." (PMID 37287910, 2023). "Using a positive whole-genome CRISPR/Cas9 library screen, and several BRCA1-mutated breast and ovarian cancer cell lines we discovered that haploinsufficiency of ZNF251 which belongs to the Kruppel-associated box (KRAB) zinc-finger gene family cluster caused resistance to multiple PARPis." (PMID 37066268, 2023). "BRCA1 pathogenic variants were detected in 11 of the 158 (7.0%) ovarian cancer cases." (PMID 35382848, 2022). "CA125 is the biomarker used for screening ovarian cancer, especially in the BRCA1/2 mutation case." (PMID 35578123, 2022). "Bilateral breast cancer (BBC), as well as ovarian cancer, are significantly associated with germline deleterious variants in BRCA1/2, while BRCA1/2 germline deleterious variants carriers can exquisitely benefit from poly (ADP-ribose) polymerase (PARP) inhibitors." (PMID 36324133, 2022). "PARPi was initially used to treat ovarian cancer patients with BRCA1 mutations." (PMID 35016681, 2022). "Indeed, it has to be underlined that, beyond breast and ovarian cancers, pathogenic variants in BRCA1 and BRCA2, as well as in CHEK2 and PALB2, have been associated with a higher risk of developing an increasing number of cancers." (PMID 35456488, 2022). "Importantly, we found that patients with both PPARGC1A and BRCA1/2 mutations were diagnosed with breast or ovarian cancer at a significantly younger age, while the effect of each gene alone was not significant." (PMID 35625955, 2022). "Women with BRCA1- or BRCA2-associated HCS have a lifetime risk of ovarian cancer between 17–44%." (PMID 35877228, 2022). "More cases with BRCA1 reversion mutations were reported in ovarian cancer than BRCA2." (PMID 36557020, 2022). "The HR repair mechanism (HRR) involves multiple proteins, and germline BRCA1/2 mutations are the most well-known genetic component of HRD in ovarian cancer, accounting for 10–15% of cases, especially for high-grade serous carcinoma (HGSOC), in which they account for 20–30% of patients." (PMID 35626108, 2022). "Furthermore, breast and ovarian cancer can be found at higher rates in patients with BRCA1 mutations that are also affected by NF-κB signaling." (PMID 36531159, 2022). "We highlighted the presence of specific mutational signatures (COSMIC signature 3) and genomic instability characteristics (LOH, TAI and LST), reflecting significant HRD, comparable with that observed in ovarian cancers with a BRCA1 or BRCA2 pathogenic variants." (PMID 35280729, 2022). "The European Society of Medical Oncology (ESMO) and NCCN of the United States stated that prophylactic RRSO may significantly reduce the risk of BC and ovarian cancer in women with BRCA1 gene mutation after the completion of reproductive needs." (PMID 35300412, 2022). "In addition, C61G (observed in Marmara, Central Anatolia and Mediterranean regions) variant in BRCA1 gene was observed with significantly low allele frequency compared to global databases (0.1614%–0.6%) which also implicated in Saudi ovarian cancer patients." (PMID 35753294, 2022). "BRCA1 is involved in maintaining genomic stability and DNA repair by homologous recombination and germline mutations leading to loss-of-function cause hereditary breast and ovarian cancer." (PMID 38836089, 2022).